MRPL23 (mitochondrial ribosomal protein L23)
Synonyms: L23mt; MRP-L23; L23MRP; RPL23L; uL23m
Tractability: Small molecule: a structure with a bound ligand is known. PROTAC: its protein half-life has been measured.
Gene: Protein-coding gene on chromosome 11 (1,947,278 to 1,986,375, forward strand). Ensembl gene ENSG00000214026.
Subcellular location: Mitochondrion
Subcellular location (Human Protein Atlas): Mitochondria; Nucleoli fibrillar center
Pathways (Reactome):
Metabolism of proteins: Mitochondrial ribosome-associated quality control; Mitochondrial translation elongation; Mitochondrial translation initiation; Mitochondrial translation termination
Gene Ontology:
Molecular function: protein binding; RNA binding; structural constituent of ribosome
Biological process: mitochondrial translation; translation
Cellular component: mitochondrial large ribosomal subunit; mitochondrion; mitochondrial inner membrane; ribosomal subunit; ribosome
Genetic constraint (gnomAD): Loss-of-function variants: 0 observed, 0.39 expected, observed/expected ratio (o/e) 0, 90% interval 0 to 1.85. That is too few expected variants to judge how well the gene tolerates losing a copy. Missense variants: 16 observed, 26.85 expected, observed/expected ratio (o/e) 0.6, 90% interval 0.4 to 0.9. Synonymous variants: 6 observed, 8.81 expected, observed/expected ratio (o/e) 0.68, 90% interval 0.37 to 1.34.
Homologues: Orthologues: mouse Mrpl23 (82% identical), rat Mrpl23 (80% identical), dog MRPL23 (79% identical), chimpanzee MRPL23 (74% identical), macaque MRPL23 (67% identical), tropical clawed frog mrpl23 (61% identical), zebrafish mrpl23 (61% identical), Drosophila melanogaster mRpL23 (41% identical), Caenorhabditis elegans mrpl-23 (35% identical).
Diseases named in the same sentence as MRPL23 in open-access papers:
MRPL23 is named in the same sentence as 14 diseases in open-access papers, as found by Europe PMC text mining. Sharing a sentence is not in itself a finding about the gene and the disease. The quoted sentences say what the papers report.
clear cell renal cell carcinoma (2 papers, 2024 to 2025). "In our previous study, we showed that clear cell renal cell carcinoma patients had lower MRPL23 expression levels than healthy controls." (PMID 41420324, 2025). "This study examines the role of MRPL23, a cellular protein, in clear-cell renal cell carcinoma (ccRCC) by comparing its levels in cancerous tissues to those in nearby healthy tissues." (PMID 39682098, 2024).
aging (1 paper, 2021). A developmental process that is a deterioration and loss of function over time. "In humans, a genetic polymorphism within the mitochondrial ribosomal protein L23 (MRPL23) gene has been shown to be associated with cognitive aging." (PMID 34122052, 2021).
gastric cancer (1 paper, 2017). A primary or metastatic malignant neoplasm involving the stomach.
glioblastoma (1 paper, 2021). The most malignant astrocytic tumor (WHO grade IV). "Furthermore, some evidence suggests that several genes expressing MRPs including bS1m (MRPS28), uS2m (MRPS2), uL23m (MRPL23), uS12m (MRPS12), bL12m (MRPL12) and mS34 (MRPS34) may be potential biomarkers for the treatment of glioblastoma with Benzyl isothiocyanate (BITC)." (PMID 34071057, 2021).
prostate adenocarcinoma (1 paper, 2025). "The mean MRPL23 expression was significantly higher in prostate adenocarcinomas than in normal tissues (FPKM 3.33 versus 3.13; P = .01)." (PMID 41420324, 2025). "Complementary TCGA analysis confirmed elevated MRPL23 mRNA levels in prostate adenocarcinomas compared with normal tissues (P = .01) and demonstrated that high expression predicted shorter disease-free survival (10-year DFS: 75.98% versus 92.92%, log-rank P = .01)." (PMID 41420324, 2025).
prostate carcinoma (1 paper, 2025). A carcinoma that arises from epithelial cells of the prostate gland. "MRPL23 is a potential prognostic biomarker in prostate cancer, linked to aggressive tumor behavior and poor outcomes." (PMID 41420324, 2025). "This study aims to evaluate the expression of MRPL23 and its association with prostate cancer progression and patient survival." (PMID 41420324, 2025). "TCGA data suggest a link between MRPL23 expression and tumor phenotype, supporting its further investigation as a potential diagnostic and prognostic biomarker in prostate cancer." (PMID 41420324, 2025). "In our cohort, MRPL23 expression was associated with prostate cancer progression and carried clear prognostic value." (PMID 41420324, 2025). "MRPL23 expression differed significantly across all tissue types, with higher levels in prostate cancer tissues compared with normal epithelium, and the highest expression observed in lymph node metastases (P < .001)." (PMID 41420324, 2025). "Our study is the first to evaluate MRPL23 expression patterns in PCa, demonstrating that it is overexpressed in prostate cancer tissues compared with normal adjacent tissue, with the highest levels observed in lymph node metastases." (PMID 41420324, 2025). "Since previous research has demonstrated the involvement of MRPL23 in the initiation and development of other tumors, analogous mechanisms may also contribute to prostate cancer biology." (PMID 41420324, 2025). "Nevertheless, recent evidence suggests that MRPL23 may contribute to cancer development through multiple pathways, potentially influencing the clinicopathological characteristics of prostate cancer." (PMID 41420324, 2025). "However, a significant gap remains in our understanding of the role of MRPL23 expression in prostate cancer." (PMID 41420324, 2025). "Mitochondrial ribosomal protein L23 (MRPL23) has recently emerged as a potential contributor to cancer progression, but its role in prostate cancer remains poorly understood." (PMID 41420324, 2025).
retinitis pigmentosa (1 paper, 2018). Retinitis pigmentosa (RP) is an inherited retinal dystrophy leading to progressive loss of the photoreceptors and retinal pigment epithelium and resulting in blindness usually after several decades. "At least three other MRP genes; MRPL9, MRPL23, and MRPL39 map to genomic regions associated with retinitis pigmentosa indicating the importance of this pathway in retinal pathology." (PMID 29739359, 2018).
schizophrenia (1 paper, 2016). A major psychotic disorder characterized by abnormalities in the perception or expression of reality. "Of the genes with significantly lower expression in males with schizophrenia, several were related to energy metabolism (ATP5B, ATP5A1, MRPL23, AFG3L2, ABCG2)." (PMID 26818902, 2016).
Wilms Tumor 2 (1 paper, 2023). "Two diseases, Familial Wilms Tumor 2 and Wilms Tumor 2, have been associated with MRPL23." (PMID 36816032, 2023).
tumor (3 papers, 2017 to 2026). "Thus, alterations in MRPL23 expression levels may be associated with carcinogenesis and enhanced tumor progression." (PMID 39682098, 2024). "Our findings show that MRPL23 protein expression is reduced in tumor tissues, while its mRNA levels are increased, linking it to specific cancer characteristics and progression." (PMID 39682098, 2024). "The analysis of the correlation between MRPL23 expression and clinicopathological characteristics revealed significant differences between MRPL23 expression status and gender, tumor grade, pT status, and disease stage." (PMID 39682098, 2024). "The goal was to assess the impact of MRPL23 expression on tumor behavior, progression, and patient outcomes." (PMID 39682098, 2024). "The positive correlation with higher tumor grades and advanced pT stages further supports the potential role of MRPL23 in promoting tumor growth and progression." (PMID 39682098, 2024). "MRPL23 expression increases with the increase in tumor grade (p = 0.0079)." (PMID 39682098, 2024). "This may indicate the significant role that MRPL23 plays in tumor biology, particularly in the context of its impact on cellular metabolism and signaling pathways related to cell proliferation and oxidative stress response." (PMID 39682098, 2024). "Since n346077 is located in the opposite strand of MRPL23 gene, whether it functions through augmenting MRPL23 tumor suppressor function will be investigated in the future." (PMID 29029442, 2017). "Further investigation into the precise roles of MRPL23 and MRPL23-AS1, especially their potential interaction in the tumor microenvironment, could provide valuable insights into the mechanisms underlying tumor progression and reveal novel therapeutic targets." (PMID 39682098, 2024). "In contrast, the analysis of the TCGA cohort showed that MRPL23 mRNA levels were significantly elevated in tumor tissues compared to non-tumorous tissues." (PMID 39682098, 2024). "In the analysis of the TCGA cohort, MRPL23 mRNA levels were significantly elevated in tumor tissues compared to normal non-tumorous tissues (p ≤ 0.0001)." (PMID 39682098, 2024).
cancer (2 papers, 2020 to 2023). A tumor composed of atypical neoplastic, often pleomorphic cells that invade other tissues. "Of note, based on the UALCAN and TNMplot.com analysis platforms, MRPL23 levels were markedly elevated in cancer specimens compared with their normal counterparts." (PMID 36830863, 2023). "MRPL23 not only promotes the metastasis of salivary adenoid cystic carcinoma, it is also related to the occurrence of liver cancer, suggesting that the same MRP can affect different cancers." (PMID 33238645, 2020).
MRPL23 also shares sentences with these, for which no sentence is quoted: lung squamous cell carcinoma (1 paper); non-small cell lung carcinoma (1); squamous cell carcinoma (1).